FOXP3 (forkhead box P3)
Diseases named in the same sentence as FOXP3 in open-access papers (continued):
Sharing a sentence is not in itself a finding about the gene and the disease.
rheumatoid arthritis (continued). "Furthermore, ASH1L, SMAD3 and FOXP3 are all downregulated in CD4+ T cells from PBMCs of patients with rheumatoid arthritis, indicating the potential significance of ASH1L/SMAD3/FOXP3 pathway in human autoimmune pathogenesis." (PMID 28598443, 2017). "Through literature reviewing, we found that kaempferol, a key ingredient in Hedyotis diffusa Willd., can enhance the suppressive function of Treg cells by inhibiting FOXP3 phosphorylation, which prevent the progression of inflammatory diseases, such as SLE and rheumatoid arthritis." (PMID 27034698, 2016). "In the synovial fluid of rheumatoid arthritis patients, the pro-inflammatory cytokine TNFα induces the expression and enzymatic activation of protein phosphatase 1 (PP1) that dephosphorylates Ser418 of FOXP3." (PMID 26441996, 2015). "Notably, treatment of rheumatoid arthritis subjects with TNF-α-antibodies restores Treg function, decreases PP1 expression, and increases FOXP3 phosphorylation." (PMID 25741338, 2015). "In addition, ectopic expression of FoxP3 conveys a Treg phenotype to CD4+ T cells, lending itself to therapeutic use in the prevention of rheumatoid arthritis (RA)." (PMID 20384988, 2010). "This CD4− cluster largely expressed Foxp3, Helios, and TIGIT as well as CD25, CD39, CTLA-4, CD71, HLA-DR, and low CD127, thus mirroring CD8+ Treg-like cells which have been described in inflamed joints of rheumatoid arthritis (RA), psoriatic arthritis (PsA), and spondylarthritis." (PMID 39101538, 2024). "In rheumatoid arthritis (RA), TNF‐α decreased the expression of Foxp3, which down‐regulated the suppressive function of Tregs." (PMID 32881301, 2020). "Rebamipide exerted beneficial effects in a mouse model of rheumatoid arthritis (RA) by regulating Th17/Treg cell imbalance by modulating STAT3 and FoxP3 expression." (PMID 27350608, 2016). "We aimed to investigate the expression of pro-inflammatory cytokine genes TNFA, IL6, IL12B, IL23, IL18 and immunoregulatory genes FOXP3, TGFB1, and IL10 in the peripheral blood of patients with rheumatoid arthritis (RA) at messenger ribonucleic acid (mRNA) level." (PMID 38534783, 2024). "Previous studies indicated an abnormal phenotype and impaired function of synovial Tregs in rheumatoid arthritis (RA) and increased FOXP3 expression in synovial CD4+ T cells in rheumatoid factor (RF)-negative RA and PsA compared to seropositive RA." (PMID 28679449, 2017).
psoriasis (97 papers, 2011 to 2025). An autoimmune condition characterized by red, well-delineated plaques with silvery scales that are usually on the extensor surfaces and scalp. "Other miRNAs implicated across diseases include miR-31 (upregulated in psoriasis T cells, affecting FOXP3 methylation), miR-24 and miR-210 (dysregulated in various contexts, with putative epigenetic targets)." (PMID 41376628, 2025). "Serum levels of IL-10 and TGF-β were measured alongside the analysis of FOXP3 variants due to their close association with FOXP3 and their significant roles in the pathogenesis of psoriasis." (PMID 40076417, 2025). "One of the earlier studies has elucidated a genetic association between the FOXP3 gene and Psoriasis in the Chinese majority population, suggesting the T allele as a contributing factor to the disease." (PMID 41346162, 2025). "Leptin as well as resistin, is involved in Foxp3 + regulatory T-cell (Treg) deficiency in psoriasis, which lead to chronic activation of effector and memory T cells." (PMID 33927259, 2021). "The molecular mechanisms by which rs3761548 polymorphisms affects Foxp3 expression has been well-characterized in psoriasis." (PMID 32612577, 2020). "CD39+ deficiency has also been recently shown in psoriasis with a significant reduction of CD39+ FOXP3+ cells observed in patients with erythrodermic and pustular psoriasis." (PMID 31277078, 2019). "Patients suffering from psoriasis are characterized by high CCL3 serum concentration that strongly correlates with increased degradation of Foxp3 mediated by K48-linked polyubiquitination." (PMID 32117202, 2019). "Moreover, in psoriasis patients, it was shown that enhanced loss of Foxp3 is linked to Treg differentiation into IL-17A producing cells." (PMID 36450783, 2022). "In line with the homeostatic importance of Tregs in psoriatic disease, we observed a relation of Foxp3 instability with loss of immune tolerance in psoriatic disease: presence of ADAMTSL5 antibodies in psoriasis and PsA reflected the balance between Foxpint and Foxp3hi Tregs." (PMID 36450783, 2022). "Increased expression of miR-4649-3p in psoriasis may lead to a decrease in Treg cell production (by suppressing FOXP3 gene) causing an exacerbation of immune response." (PMID 33356031, 2021). "FOXP3 nuclear translocation was mediated by an interaction with pc-Jun induced by JNK, and it is speculated that mutations in FOXP3 prevent its interaction with c-Jun and nuclear translocation, leading to Treg dysfunction and promotion of psoriasis." (PMID 32252279, 2020). "Furthermore, retinoic acid, which has been used for psoriasis, is secreted by a particular subset of DCs in the gut-associated lymphoid tissue, inducing Foxp3-expresssing cells from naïve T cells." (PMID 33202847, 2020). "IL-17-producing FOXP3+ T cells were recently associated with psoriasis and systemic sclerosis." (PMID 31354747, 2019). "This study aims to evaluate the impact of MetS on immunological markers (IL-17, IL-23, and FOXP3+ regulatory T cells), disease severity, and quality of life (QoL) among patients with psoriasis." (PMID 40584971, 2025). "Previous studies have suggested a potential role of FOXP3+ in the pathogenesis of psoriasis through the IL-6 and TGF-β pathways." (PMID 40584971, 2025). "This aligns with the earlier research that demonstrated decreased FOXP3+ expression in the peripheral circulation of psoriasis patients, although the relationship with disease severity has been inconsistent." (PMID 40584971, 2025). "The variation in association patterns across populations underscores the complexity of FOXP3-mediated immune regulation in psoriasis." (PMID 40076417, 2025). "This study demonstrated immune dysregulation in psoriasis patients with MetS, as evidenced by a significant reduction in FOXP3+ expression." (PMID 40584971, 2025).
psoriasis (continued). "Additionally, the functional impact of the FOXP3 variants, such as their influence on mRNA or protein expression, was not assessed, limiting mechanistic insights into how these variants may contribute to the pathogenesis of psoriasis." (PMID 40076417, 2025). "This meant that FOXP3 expression was lower and there were fewer Tregs cells, which helped psoriasis get worse." (PMID 39296901, 2024). "In psoriasis lesions, forkhead box transcription factor P3 (FOXP3)-positive regulatory T (Treg) cells can differentiate into highly pro-inflammatory, triple-positive IL-17A+/FOXP3+/CD4+ Th17 cells, thereby sustaining the overall inflammatory process." (PMID 39684717, 2024). "One of the upregulated genes was Izumo1r (upregulated 5.04 fold, P<0.0001), which is expressed in Foxp3+ Treg cells and was recently shown to facilitate Treg tight contacts with γδT cells to mediate psoriasis-like inflammation in the dermis." (PMID 38562928, 2024). "In a psoriasis mouse model, cutaneous application of sodium butyrate increased IL-10 and FOXP3 expression in T cells and reduced inflammation." (PMID 37953417, 2024). "Forkhead box protein-3 (FOXP3) is a marker of regulatory T cells (Tregs), especially CD4+ Tregs, however, FOXP3 is also expressed in CD8+ T cells and FOXP3 expression is increased in psoriasis lesions." (PMID 38915827, 2024). "AOA significantly reduced the expansion of IL-17A-producing Th17 cells and significantly induced the expansion of Foxp3+ Treg cells in psoriasis-like skin." (PMID 37649889, 2023). "This technique also helped to identify a CD4+ Treg cell population in psoriasis that was noted by the expression of FOXP3, TIGIT, CTLA4, IL2RA (CD25), and IKZF2." (PMID 37270497, 2023). "It has been well established that CD4 + Foxp3 Treg cells play an indispensable role in suppressing autoimmune inflammatory responses, including psoriasis." (PMID 37506136, 2023). "In a model of imiquimod-induced psoriasis in mice, it was described an increase of Foxp3+ Tregs in the skin and restoration of their suppressive function following use of IL-17 or IL-23 blocking antibodies but not with an anti-TNF-α treatment." (PMID 36901778, 2023). "Taken together, these results highlight the potential of the dNP2-ctCTLA-4 peptide to induce Foxp3+ Treg cells in vivo, consequently ameliorating psoriasis-like skin inflammation." (PMID 37818377, 2023). "There is compelling evidence that CD4+Foxp3+ regulatory T cells (Tregs) are indispensable in the inhibition of autoimmune inflammatory responses, including psoriasis." (PMID 35464441, 2022). "In contrast to the increase of Th1 and Th17 cells, the level of CD4+ Foxp3+ T cells was reduced in psoriasis-induced mice." (PMID 36591260, 2022). "Bath‐psoralen UV‐A therapy induced circulating Foxp3+ Treg cells in 10 patients with psoriasis who were first treated with phototherapy." (PMID 36151864, 2022). "In the posttreatment biopsy specimens of those patients, FoxP3 mRNA levels remained high in the resolved psoriasis skin." (PMID 36110854, 2022). "Functional inhibition of Th1 and Th17 cells by ndSTAT1-TMD in the psoriasis-induced mice substantially restored the level of CD4+ Foxp3+ T cells." (PMID 36591260, 2022). "Narrow-band UVB therapy increased Treg number and Foxp3 mRNA levels in peripheral blood mononuclear cells of patients with psoriasis and reduced Th1/Th17 cells." (PMID 34501328, 2021). "In the CD3+ T-cells of psoriasis patients, the expression level of PPARγ was reduced in 3.4 ± 0.4 times and FOXP3—in 5.4 ± 0.16 times compared to healthy volunteers." (PMID 34445309, 2021). "This work aimed to evaluate the role of miRs (miR-4649-3p, miR-6867-5p, miR-4296, miR-210, and miR-1910-3p) that target the FOXP3 mRNA and IL-17A mRNA in psoriasis." (PMID 33356031, 2021).
psoriasis (continued). "The pan-HDAC inhibitor trichostatin A acts on human peripheral blood-derived CD4+CD25+Foxp3+ Tregs, reversing their conversion into Th17 cells and increasing Foxp3 expression in healthy controls and in patients with psoriasis." (PMID 34501328, 2021). "IL-6, which is a critical cytokine for Th17 differentiation, inhibits Treg cells by inhibiting the expression of Foxp3 in psoriasis pathogenesis." (PMID 34975883, 2021). "Topical application of sodium butyrate to imiquimod-induced psoriasis-like dermatitis in mice increased IL-10 and Foxp3 transcripts and reduced inflammation and IL-17A transcripts." (PMID 34501328, 2021). "Patients with psoriasis manifest functional defects in CD4+CD25+ forkhead box protein 3 (Foxp3)+ regulatory T cells (Tregs), which suppress the excess immune response and mediate homeostasis." (PMID 34501328, 2021). "The unstable expression (downregulation) of Foxp3 reflects the dysfunction of Treg cells in psoriasis, and numerous upstream regulators have been reported." (PMID 34975883, 2021). "TSDR hypermethylation is associated with chromatin condensation and downregulation of Foxp3 expression; therefore, the results indicate downregulation of Foxp3 and reduction of Tregs in psoriasis patients’ blood." (PMID 34501328, 2021). "Anti-IL-23p19 antibody treatment in an imiquimod-induced psoriasis mouse model increased the number of Foxp3+ cells in the lesions, and adoptive transfer of Tregs from anti-IL-23p19 antibody-treated mice improved psoriasis-like dermatitis in the donor mice." (PMID 34501328, 2021). "In our study, it was shown that GA inhibited the phosphorylation of mTOR and increased the CD4+FoxP3+ Treg frequency in spleen and lymphonodus in mice with imiquimod-induced psoriasis." (PMID 32908937, 2020). "On the other hand, the number of CD25+Foxp3+ T cells (Tregs) were dereased in MIQ psoriasis mice comparing to control." (PMID 32102363, 2020). "A similar finding has been recently described in a psoriasis murine model where the administration of anti- IL-17A or IL-23p19 induced a significant increase in the number or Foxp3+ IL-10+ Treg cells." (PMID 32630692, 2020). "Taken together, our data provides evidence that the percentage of CD14+HLA-DR−/low MDSC/ CD14+ cells and TNF-α and FOXP3 mRNA expression levels in PBMCs are potential biomarkers for making a distinction between the psoriasis TCM BS syndrome and BH syndrome." (PMID 32382290, 2020). "The mRNA levels of IL-17A, IL-22, IL-23, RORγt, and IFN-γ were increased in the lesional skin of psoriasis patients, whereas Foxp3, a vital transcriptional factor of Treg cells, was decreased in psoriasis patients." (PMID 31440249, 2019). "A study performed on patients with plaque and guttate psoriasis found higher levels of FOXP3 positive Treg cells in skin lesions and peripheral blood of patients with plaque type psoriasis, the levels being positively correlated with disease severity." (PMID 30744173, 2019). "This phenomenon is mediated by the activation of the protein kinase B (PKB)α/Akt1 pathway, but the precise mechanism of how CCL3 and PKB induce polyubiquitination of Foxp3 in psoriasis is still under investigation." (PMID 32117202, 2019). "Other authors also identified higher levels of FOXP3 positive Treg cells and Th-17 in the psoriatic lesions and the peripheral blood, thus indicating a possible role in the pathogenesis of psoriasis." (PMID 30744173, 2019). "Our results showed that the addition of TSP-1 induced a significant increment in the percentage of Treg (CD25+ FoxP3+) cells in samples from psoriasis patients (Friedman test p = 0.03)." (PMID 31214201, 2019). "The mRNA levels of IL-21, IL-21R, IL-17A, IL-22, IL-23, RORγt, and IFN-γ were increased, whereas the mRNA level of Foxp3 was decreased in the PBMCs of psoriasis patients." (PMID 31440249, 2019).
psoriasis (continued). "It was recently reported that Cal-BDP combination therapy increases CD4+CD25+Foxp3+CD127lo Tregs and reduces Th17 cells in the blood and skin lesions of patients with psoriasis, suggesting that Cal-BDP combination therapy restores the Treg-T17 balance." (PMID 31705000, 2019). "We also found that the expression of Foxp3, which is essential for the differentiation and function of Treg cells, was reduced after the treatment with IL-21, both in psoriasis patients and healthy individuals." (PMID 31440249, 2019). "CD4+CD25+Foxp3+ Tregs can differentiate into IL-17A-producing Th17 cells in patients with psoriasis." (PMID 30258447, 2018). "Recently, N-3 PUFAs have been reported to increase the number of CD4+CD25+Foxp3+Treg cells and to decrease Th17 cell differentiation and IL-17 production in other disease models including encephalomyelitis and psoriasis." (PMID 29543869, 2018). "Previous studies have shown that induction of endogenous CD4+CD25+Foxp3+ Tregs or reversal of Th17/Treg imbalance ameliorates IMQ-induced psoriasis in mice." (PMID 30258447, 2018). "To dissect the function of Foxp3+ T reg cells during psoriasis development, we depleted T reg cells in the imiquimod (IMQ)-induced model of psoriasiform skin inflammation." (PMID 29980582, 2018). "Etanercept treatment induced transcriptional levels of Foxp3, STAT3 and STAT4 mRNA in responding psoriasis patients and increased the Foxp3/RORγt ratio in RA patients." (PMID 28098832, 2017). "Several researchers found decreased CD4+CD25+FOXP3+ T circulating cells both numerically and functionally in psoriasis patients." (PMID 28042206, 2016). "Our study revealed increased transcripts levels of IL17A, IFNG, and FOXP3 in moderate-severe psoriasis patients." (PMID 28042206, 2016). "Human mucosal Foxp3+Tregs express IL-17A in inflammatory conditions, such as periodontitis, psoriasis and IBD." (PMID 25790134, 2015). "In addition, resistin may play a role in Foxp3+ regulatory T-cell (Treg) deficiency in psoriasis." (PMID 25980409, 2015). "By inducing and maintaining immunological tolerance, Foxp3+ Treg cells inhibit infiltration of Foxp3+ lymphocytes into skin lesions in psoriasis patients." (PMID 25980409, 2015). "We assessed CD4+CD25+ (Forkhead box protein 3) Foxp3+ Treg in the peripheral blood of psoriasis patients before and after bath-PUVA therapy." (PMID 23365685, 2013). "M2‐like macrophages polarized by Foxp3‐ Treg‐of‐B cells ameliorate imiquimod‐induced psoriasis." (PMID 40539722, 2025). "Furthermore, the relative number of CD4+Foxp3+CD25+ cells showed increases in psoriasis mice treated with anti-IL-2/IL-2 complex as compared to other groups." (PMID 41254515, 2025). "In psoriasis patients, FOXP3+ Tregs may undergo differentiation into IL-17A-producing cells, indicating a loss of their regulatory function." (PMID 40584971, 2025). "We identified GZMB, GNAS, GBP5, FOXP3, LSP1 and CD81 as characteristic genes of psoriasis-associated CD8+ T cells, among which, Granzyme B (GzmB), a serine protease, is produced by natural killer (NK) cells and CD8+ T cells, and is an vital mediator of skin injury, inflammation and repair." (PMID 38915827, 2024). "Also, the methylation level of FOXP3 in Tregs cells from people with psoriasis was much higher than that in healthy controls." (PMID 39296901, 2024). "Therefore, the study of the proportion of Foxp3 + CD4 + Treg cells represents an entry point for the investigation of the pathogenesis of psoriasis and the treatment with targeted agents." (PMID 37506136, 2023). "T regs in psoriasis patients have been reported to have reduced suppressive activity that normalizes with sodium butyrate administration and IL-10 levels and expression of Foxp3, IL-17, and IL-6 in psoriatic skin lesions." (PMID 37623895, 2023). "In addition, resistin can inhibit the proliferation of Foxp3+ regulatory T (Treg) cells in psoriasis." (PMID 36675592, 2023).